SLC26A5 (solute carrier family 26 member 5)
Description:
Voltage-sensitive motor protein that drives outer hair cell (OHC) electromotility (eM) and participates in sound amplification in the hearing organ (By similarity). Converts changes in the transmembrane electric potential into mechanical displacements resulting in the coupling of its expansion to movement of a charged voltage sensor across the lipid membrane (By similarity). The nature of the voltage sensor is not completely clear, and two models compete. In the first model, acts as an incomplete transporter where intracellular chloride anion acts as extrinsic voltage sensor that drives conformational change in the protein which is sufficient to produce a length change in the plane of the membrane and hence in the length of the OHC (By similarity). The second model in which multiple charged amino acid residues are distributed at the intracellular and extracellular membrane interfaces that form an intrinsic voltage sensor, whose movement produces the non-linear capacitance (NLC). However, the effective voltage sensor may be the result of a hybrid voltage sensor, assembled from intrinsic charge (charged residues) and extrinsic charge (bound anion) (By similarity). Notably, binding of anions to the anion-binding pocket partially neutralizes the intrinsic positive charge rather than to form an electrically negative sensor, therefore remaining charge may serve as voltage sensor that, after depolarization, moves from down (expanded state) to up (contracted) conformation, which is accompanied by an eccentric contraction of the intermembrane cross-sectional area of the protein as well as a major increase in the hydrophobic thickness of the protein having as consequences the plasma membrane thickening and the cell contraction after membrane depolarization. The anion-binding pocket transits from the inward-open (Down) state, where it is exposed toward the intracellular solvent in the absence of anion, to the occluded (Up) state upon anion binding. Salicylate competes for the anion-binding site and inhibits the voltage-sensor movement, and therefore inhibits the charge transfer and electromotility by displacing Cl(-) from the anion-binding site and by preventing the structural transitions to the contracted state. In addition, can act as a weak Cl(-)/HCO3(-) antiporter across the cell membrane and so regulate the intracellular pH of the outer hair cells (OHCs), while firstly found as being unable to mediate electrogenic anion transport (By similarity). Moreover, supports a role in cardiac mechanical amplification serving as an elastic element to enhance the actomyosin-based sarcomere contraction system (By similarity).
Synonyms: PRES; DFNB61; PRESTIN
Tractability: Small molecule: a structure with a bound ligand is known. Antibody: UniProt places it where antibodies can reach, with high confidence; UniProt predicts a signal peptide or a membrane-spanning region; its Gene Ontology location is reachable by antibodies, with medium confidence.
Gene: Protein-coding gene on chromosome 7 (103,352,730 to 103,446,207, reverse strand). Ensembl gene ENSG00000170615.
Subcellular location: Lateral cell membrane
Pathways (Reactome):
Sensory Perception: Sensory processing of sound by outer hair cells of the cochlea
Gene Ontology:
Molecular function: protein binding; protein homodimerization activity; chloride:bicarbonate antiporter activity; oxalate transmembrane transporter activity; sulfate transmembrane transporter activity; identical protein binding; secondary active sulfate transmembrane transporter activity; spectrin binding
Biological process: sensory perception of sound; bicarbonate transport; chloride transmembrane transport; chloride transport; oxalate transport; sulfate transmembrane transport; cochlea development; fructose transmembrane transport; monoatomic anion transmembrane transport; monoatomic ion transmembrane transport; negative regulation of monoatomic ion transmembrane transport; positive regulation of cell motility; positive regulation of cell size; response to auditory stimulus; response to ischemia; response to potassium ion; response to salicylic acid; response to salt; response to thyroid hormone; response to xenobiotic stimulus; transmembrane transport
Cellular component: lateral plasma membrane; basolateral plasma membrane; lateral wall of outer hair cell; membrane; plasma membrane
Genetic constraint (gnomAD): Loss-of-function variants: 42 observed, 70.99 expected, observed/expected ratio (o/e) 0.59, 90% interval 0.46 to 0.76. The upper end of that interval is the gene's LOEUF score, 0.76, which puts it in group 3 of 6, group 1 being the genes least tolerant of losing a copy. Missense variants: 730 observed, 900.47 expected, observed/expected ratio (o/e) 0.81, 90% interval 0.76 to 0.86. Synonymous variants: 311 observed, 334.78 expected, observed/expected ratio (o/e) 0.93, 90% interval 0.85 to 1.02.
Gene-disease validity (ClinGen):
ClinGen rates the evidence that SLC26A5 causes each of these diseases.
nonsyndromic genetic hearing loss (autosomal recessive): Limited.
Homologues: Orthologues: chimpanzee SLC26A5 (99% identical), macaque SLC26A5 (99% identical), guinea pig SLC26A5 (96% identical), pig SLC26A5 (95% identical), rabbit SLC26A5 (95% identical), mouse Slc26a5 (95% identical), rat Slc26a5 (94% identical), dog SLC26A5 (92% identical), tropical clawed frog slc26a5 (56% identical), zebrafish slc26a5 (52% identical). Paralogues in human: SLC26A6 (39% identical), SLC26A3 (37% identical), SLC26A4 (36% identical), SLC26A9 (34% identical), SLC26A2 (34% identical), SLC26A1 (30% identical), SLC26A8 (27% identical), SLC26A7 (26% identical), SLC26A11 (21% identical).
Diseases named in the same sentence as SLC26A5 in open-access papers:
SLC26A5 is named in the same sentence as 23 diseases in open-access papers, as found by Europe PMC text mining. Sharing a sentence is not in itself a finding about the gene and the disease. The quoted sentences say what the papers report.
hearing loss (14 papers, 2005 to 2022). "We also identified variants and genes that cause recessive hearing loss (GJB2 Gly12fs and SLC26A5 pLOF+strict deleterious missense mutations), associated with increased risk (OR~1.2–1.3) for hearing loss in heterozygous carriers." (PMID 35661827, 2022). "A limited number of SLC26A5 mutations has been identified in patients with hearing loss; one of these mutations was linked to autosomal recessive deafness DFNB61 but later was found non‐pathogenic." (PMID 35143116, 2022). "This is the first report of mutations in ACTG1, POU4F3, and SLC26A5 in Japanese families with hearing loss." (PMID 24164807, 2013). "In humans, a single nucleotide change in SLC26A5, encoding prestin, has been reported in association with hearing loss." (PMID 16086836, 2005). "Only one of the four hearing impaired carriers of the SLC26A5 IVS2-2A>G DNA sequence variation identified in this study reported a history of hearing loss in a parent." (PMID 16086836, 2005). "SLC26A4 and SLC26A5 genes are risk loci for human asthma and hearing loss, respectively." (PMID 35433778, 2022). "Due to the limited number of patients, whether any of the identified SLC26A5 mutations are true causes of hearing loss remains unclear." (PMID 35143116, 2022). "Genetic variations in SLC26A5 are associated with hearing impairment." (PMID 35658052, 2022). "Particularly intriguing is the hypothesis of a possible dysfunction of SLC26A4 and SLC26A5 mediated by OS in noise‐induced and/or age‐related hearing loss." (PMID 35143116, 2022). "SLC26A5 encodes an anion transporter molecule responsible for electromotility in mammalian auditory sensory hair cells, and mutations in the human gene have been associated with hearing loss (autosomal recessive deafness; OMIM 604943)." (PMID 33243158, 2020). "The results of gene expression analysis of each cochlear turn showed that 4 ADNSHL genes (Pou4f3, Slc17a8, Tmc1, and Crym) and 9 autosomal recessive non syndromic hearing loss genes (Otof, Strc, Ush1c, Pcdh15, Grxcr1, Dfnb59, Slc26a5, Lhfpl5, and Ptprq) were changed 2-fold or more." (PMID 24676347, 2014). "However, linkage studies of hearing impaired families have failed so far to map SLC26A5 as a locus associated with human hearing loss." (PMID 19492055, 2009). "Although these data fail to support a hypothesis that SLC26A5 acts as a modifier gene of GJB2-related hearing loss, the sample size is small and investigation of a larger population might be more informative." (PMID 19492055, 2009). "Further investigation is needed into what role, if any, the IVS2-2A>G variation in SLC26A5 might have in human hearing loss." (PMID 19492055, 2009). "Haplotype analysis of SLC26A5 was conducted to determine whether novel or unusual haplotypes or haplotype blocks occurred in the patient population that might suggest an association of particular SLC26A5 alleles with hearing loss." (PMID 19492055, 2009). "In this study, we screened the GJB2, GJB3, GJB6, SLC26A4, SLC26A5 IVS2-2A>G and mitochondrial genes to determine the etiology of hearing loss in eastern China." (PMID 23554706, 2011). "Similar to that of the SLC26A5 IVS2-2A>G mutation, the association between mtDNA mutation and hearing loss has also a special ethnic difference." (PMID 23554706, 2011). "Curiously, SLC26A5 has not been mapped by traditional linkage analysis in any of the families with hereditary hearing loss that have so far been studied worldwide (Van Camp G, Smith RJH." (PMID 16086836, 2005). "Other members of the solute carrier family (SLC22A4, SLC26A5, SLC17A8, SLC12A2) have also been associated with non-syndromic hearing loss (hereditaryhearingloss.org)." (PMID 35741759, 2022).
deafness (12 papers, 2011 to 2022). An inherited or acquired condition characterized by the complete loss of the ability to hear from one or both ears. "Of the genes misregulated in Mir183/96dko homozygotes, five are known deafness genes; Myo3a, Slc26a5 and Tmc1 underlie deafness in mice and humans, while mutations in Sema3e cause deafness in people, and mice lacking Ocm exhibit progressive hearing loss." (PMID 33318051, 2020). "Firstly, some of the genes are independently known to be involved in hearing, such as Fgf8, Slc26a5 (prestin), Pou4f3 and Gfi19, 10, 39, 40, suggesting that other genes in the network may also underlie deafness." (PMID 26988146, 2016). "Furthermore, associations overlapped with human congenital non-syndromic deafness loci and associations were found that were proximal to genes with determined functional roles in human auditory mechanotransduction, such as SLC26A5, which encodes the motor protein of the outer hair cells, prestin." (PMID 34847940, 2021). "Twenty-five genes were present in both male and female hearing difficulty high variant load lists, including seven deafness genes (CLIC5, MYH14, COL9A3, ELMO3, FSCN2, GJB2, SLC26A5)." (PMID 35761239, 2022). "The regulatory network generated from Mir96Dmdo expression data includes a number of genes known to be involved in deafness – such as Ptprq, Gfi1, Kcna10 and Slc26a5 – as well as new candidate genes." (PMID 33318051, 2020). "Of them, 9 deafness genes expressed more in the apical turn (Pou4f3, Slc17a8, Tmc1, Crym, Otof, Ush1c, Pcdh15, Slc26a5, and Lhfpl5) and six were internal controls (Gapdh, Actb, Rps17, Rpl30, Atp6, and Ipo8)." (PMID 24676347, 2014). "This mutation alters the function of miR-96 and their consequent gene expression profile in the mouse organ of Corti such as oncomodulin (Ocm), prestin (Slc26a5), and growth factor independent 1(Gfi1) which have been known to result in deafness and hair cell degeneration." (PMID 35546217, 2022). "This makes SLC26A5 (OMIM No. 604943), the restricted expression of prestin in the outer hair cells of the cochlea, a strong candidate for human deafness." (PMID 23554706, 2011).
Pendred syndrome (3 papers, 2010 to 2022). Pendred syndrome (PDS) is a clinically variable genetic disorder characterized by bilateral sensorineural hearing loss and euthyroid goiter. "SLC26A5 has been implicated in non-syndromic SNHL whereas SLC26A4 gene mutations are associated with both autosomal recessive non-syndromic SNHL (DFNB4) and Pendred syndrome." (PMID 20668687, 2010).
Calcium oxalate nephrolithiasis (1 paper, 2025). The presence of calcium- and oxalate-containing calculi (stones) in the kidneys. "In contrast, the Drosophila melanogaster homolog of human SLC26A5/6, dPrestin, promotes the formation of calcium oxalate stones in the Malpighian tubules in a dietarily-induced model of calcium oxalate nephrolithiasis." (PMID 40991662, 2025).
nonsyndromic hearing loss (1 paper, 2023). "Mutations in SLC26A5 (aka Prestin) are associated with familial nonsyndromic hearing loss in humans." (PMID 38094513, 2023).
SLC26A5 also shares sentences with these, for which no sentence is quoted: infection (4 papers); Hearing impairment (3); Allergy (2); autosomal recessive deafness (2); diastrophic dysplasia (2); age (1); asthma (1); chronic hepatitis B virus infection (1); Congenital chloride diarrhea (1); COVID-19 (1); deafness autosomal dominant 10 (1); hepatitis B (1); liver disease (1); liver fibrosis (1); nephrolithiasis (1); sensorineural hearing loss (1); thalassemia (1); Tinnitus (1).